CXCL1 (C-X-C motif chemokine ligand 1)
Description:
Has chemotactic activity for neutrophils. May play a role in inflammation and exerts its effects on endothelial cells in an autocrine fashion. In vitro, the processed forms GRO-alpha(4-73), GRO-alpha(5-73) and GRO-alpha(6-73) show a 30-fold higher chemotactic activity.
Synonyms: MGSA; NAP-3; GRO1; GROA; SCYB1; MGSA-a; FSP
Tractability: Antibody: its Gene Ontology location is reachable by antibodies, with high confidence; UniProt places it where antibodies can reach, with medium confidence; UniProt predicts a signal peptide or a membrane-spanning region.
Gene: Protein-coding gene on chromosome 4 (73,869,392 to 73,871,308, forward strand). Ensembl gene ENSG00000163739.
Subcellular location: Secreted
Pathways (Reactome):
Immune System: Interleukin-10 signaling; Neutrophil degranulation
Signal Transduction: Chemokine receptors bind chemokines; G alpha (i) signalling events
Gene Ontology:
Molecular function: protein binding; chemokine activity; enzyme activator activity; growth factor activity; signaling receptor binding
Biological process: actin cytoskeleton organization; chemotaxis; G protein-coupled receptor signaling pathway; inflammatory response; intracellular signal transduction; negative regulation of cell population proliferation; nervous system development; signal transduction; cell chemotaxis; defense response; immune response
Cellular component: extracellular region; specific granule lumen; tertiary granule lumen
Genetic constraint (gnomAD): Loss-of-function variants: 9 observed, 13.02 expected, observed/expected ratio (o/e) 0.69, 90% interval 0.42 to 1.21. The upper end of that interval is the gene's LOEUF score, 1.21, which puts it in group 5 of 6, group 1 being the genes least tolerant of losing a copy. Missense variants: 146 observed, 137.57 expected, observed/expected ratio (o/e) 1.06, 90% interval 0.93 to 1.22. Synonymous variants: 78 observed, 59.38 expected, observed/expected ratio (o/e) 1.31, 90% interval 1.09 to 1.59.
Homologues: Orthologues: chimpanzee CXCL1 (100% identical), macaque CXCL1 (90% identical). Paralogues in human: CXCL2 (90% identical), CXCL3 (87% identical), PPBP (50% identical), CXCL5 (44% identical), CXCL6 (40% identical), CXCL8 (38% identical), PF4 (37% identical), CXCL9 (35% identical), PF4V1 (35% identical), CXCL11 (24% identical), CXCL13 (23% identical), CXCL10 (22% identical).
Diseases named in the same sentence as CXCL1 in open-access papers:
CXCL1 is named in the same sentence as 578 diseases in open-access papers, as found by Europe PMC text mining. Sharing a sentence is not in itself a finding about the gene and the disease. The quoted sentences say what the papers report.
breast carcinoma (227 papers, 2009 to 2026). "CXCL1 can be a marker of cardiotoxicity caused by doxorubicin, as shown in a study of breast cancer patients who were treated with this chemotherapeutic agent." (PMID 40427171, 2025). "XIAOPI was confirmed to inhibit breast cancer lung metastasis by inhibiting CXCL1 secretion from tumor-associated macrophages." (PMID 40028340, 2025). "Clinical investigation also revealed that CXCL1 was an independent risk factor for breast cancer prognosis and positively correlated with IGF1R and HMGB1 expression." (PMID 39394189, 2024). "Accordingly, the inhibition of NF-κB blocks CXCL1-induced SOX4 overexpression, increases the E-cadherin and reduces both vimentin and β-catenin expression, underlying the importance of CXCL1/SOX4/NF-κB axis in sustaining breast cancer." (PMID 38397187, 2024). "Breast cancer chemotherapy resistance is believed to be influenced by tumor-associated macrophages (TAMs), by which C-X-C motif chemokine ligand 1 (CXCL1) is the most abundant cytokine secreted." (PMID 39394189, 2024). "Multivariate COX regression analysis further suggested that tumor stage and CXCL1 expression were independent risk factors determining breast cancer prognosis." (PMID 39394189, 2024). "In breast cancer, CXCL1 originating from tumor-associated macrophages (TAMs) promotes tumor metastasis by activating signaling pathways such as NF-κB/SOX4." (PMID 38791448, 2024). "Breast cancer cells from the same co-cultures caused increased pulmonary metastases and high numbers of metastatic nodules in mice, while a CXCL1 blocking antibody reversed those effects." (PMID 39044824, 2024). "Breast cancer cells cause an increase in CXCL1 expression in lymphatic endothelial cells (LEC), which causes breast cancer cells to migrate into lymphatic vessels, resulting in lymph node metastasis." (PMID 37108425, 2023). "Another factor that decreases CXCL1 expression in breast cancer cells is either decreased expression or loss of HER2 expression." (PMID 37108425, 2023). "Due to the significant influence of CXCL1 in tumorigenesis, obesity in breast cancer patients is associated with a worse prognosis." (PMID 37108425, 2023). "CXCL1 causes an increase in the adhesion of circulating breast cancer cells to human pulmonary microvascular endothelial cells, that is, to the walls of blood vessels in the lungs." (PMID 37108425, 2023). "CXCL1 can also indirectly cause angiogenesis by inducing an increase in VEGF expression in breast cancer cells." (PMID 37108425, 2023). "Considering all breast cancer cases, the association between the level of CXCL1 expression in the tumor and prognosis varies depending on the literature source." (PMID 37108425, 2023). "The tumor-associated macrophages-derived CXCL1 is involved in the regulation of breast cancer metastasis by activating the NF-κB/SOX4 pathway." (PMID 36614235, 2023). "After binding to its receptor CXCR2, CXCL1 activates many pathways implicated in breast cancer including phosphatidylinositol-4,5-bisphosphate 3-kinase-γ (PI3Kγ)/Akt, MAP kinases such as ERK1/ERK2 or phospholipase-β (PLCβ) signaling pathways." (PMID 38022682, 2023). "Conversely, higher CXCL1 expression is associated with a worse prognosis for patients with basal breast cancer." (PMID 37108425, 2023). "Studies on breast cancer cells showed that a breast cancer susceptibility gene 1 (BRCA1) complex with GATA-binding protein 3 (GATA3) reduced CXCL1 expression." (PMID 35054978, 2022). "It is unfortunate that no data exist on the diagnostic criteria of serum/plasma level of CXCL1 in oncology patients with breast cancer or other types of cancer." (PMID 36431173, 2022). "C-X-C motif chemokine ligand 1 (CXCL1), as a relatively specific biomarker of tumor-associated macrophages (TAMs), promotes breast cancer migration and invasion via NF-κB/SOX4 activation." (PMID 35443644, 2022).
breast carcinoma (continued). "Studies have also shown that knocking down CXCL1/CXCL2 by short hairpin RNA caused a reduction in metastasis from mammary tumors to the lungs." (PMID 36612163, 2022). "Recent research indicates that CXCL1 from tumor-associated macrophages acts via downstream NFKB/SOX4 signaling in breast cancer." (PMID 33256011, 2020). "Previous studies indicated that CXCL1 promotes tumor growth and is associated with poor survival in gastric cancer, breast cancer, and hepatocellular carcinoma." (PMID 32337262, 2020). "In a microarray data series of 201 genetically engineered mouse models of breast cancer, similar associations for Cxcl1 were also identified." (PMID 32634121, 2020). "CXCL1 has been found to be highly expressed within breast cancer stroma and is inversely associated with TGF-β signal protein, with TGF-β shown to negatively regulate CXCL1 expression." (PMID 33256011, 2020). "Together, suggest that high local or systemic IL-1β plus CXCL1 plus CCL2 plus S100A8 plus VEGF plus IL8 in breast cancer patients represents a diagnostic biomarker for the existence of IRISOE TNBC tumor, and propensity to reduced RFS, DMFS, or OS." (PMID 29262555, 2017). "A previous study identified a paracrine network between tumor and stromal cells comprising of CXCL1 and 2, which indicated that lung metastasis was associated with chemotherapy resistance in breast cancer." (PMID 25411894, 2015). "Here we report that elevated CXCL1 expression in breast cancer stroma is associated with tumor recurrence and decreased patient survival." (PMID 25344051, 2014). "Based on these findings, we conclude that human HER2+ breast cancer associated with decreased TGFβ signaling would also correlate with deceased expression of CXCL1/5 chemokines and increased VEGF." (PMID 25280532, 2014). "Moreover, analysis of breast cancer patient samples showed an inverse association between the plasma CXCL1 levels and STK11 expression." (PMID 41051525, 2025). "Also, suppression of TGF-β seems to lead to higher CXCL1 expression, which appears to be associated with metastases in breast cancer." (PMID 40662776, 2025). "With comorbidities, the level of Groα/CXCL1 could be further increased significantly, which could argue the further increased risk of breast cancer." (PMID 38541912, 2024). "Additionally, TAMs/CXCL1 silence improved paclitaxel chemosensitivity by suppressing autophagy in breast cancer mice xenografts, and clinical studies further linked CXCL1 to IGF1R/HMGB1 signaling, as well as shorter free survival of recurrence." (PMID 39394189, 2024). "For ERα-positive breast cancer, depending on the work cited, high CXCL1 expression in the tumor may be associated with either a worse or better prognosis." (PMID 37108425, 2023). "Given that PMN components might provide insight into the early prognosis of invasive breast cancer, it is of significance to investigate the underlying mechanisms regulating the CXCL1-induced accumulation of MDSCs." (PMID 37210553, 2023). "The level of CXCL1 in the blood may be associated with the prognosis of breast cancer patients, with a higher circulating level of CXCL1 indicating a worse prognosis." (PMID 37108425, 2023). "Given the vast amount of information available, this review focuses on the role of CXCL1 in cancer-related processes and its association with clinical aspects of reproductive cancers such as breast cancer, cervical cancer, endometrial cancer, ovarian cancer, and prostate cancer." (PMID 37108425, 2023). "Therefore, a positive feedback loop is formed between cancer-associated adipocytes and breast cancer cells; CXCL1 is one of the components of the loop." (PMID 37108425, 2023). "Also, in vivo breast cancer xenografts demonstrated that CXCL1 silencing in tumor-associated macrophages results in a significant reduction in breast cancer growth and metastatic burden." (PMID 35585513, 2022).
breast carcinoma (continued). "Tumor-associated macrophages could secret CXCL1, which promotes breast cancer metastasis by the NF-κB/SOX4 pathway." (PMID 34439306, 2021). "Indeed, CXCL1 derived from tumor-associated macrophages proved to be an important factor in the promotion of breast cancer." (PMID 34269159, 2021). "Furthermore, the expression of CXCL1 was implicated as a favorable factor in the overall survival of breast cancer patients." (PMID 33959656, 2021). "Additionally, we demonstrated that the expression of CXCL1, 2, 5, 8, 12, 13, and 14 was closely associated with the stage of breast cancer." (PMID 34439306, 2021). "Previously we demonstrated that XIAOPI formula could inhibit breast cancer lung metastasis via inhibiting tumor associated macrophages (TAMs)-secreted CXCL1." (PMID 32213179, 2020). "In the breast cancer tissue from 121 patients, we examined whether CXCL1 expression was associated with clinicopathological parameters." (PMID 30158589, 2018). "Clinically, CXCL1 has been implicated in breast cancer lymphoid metastasis and poor OS, so it may be a prognostic biomarker of breast cancer." (PMID 30158589, 2018). "Furthermore, CXCL1-mediated myeloid cells infiltration is associated with therapeutic response in breast cancer." (PMID 27446967, 2016). "Overexpression of CXCL1 in the breast cancer stroma is associated with poor patient prognosis." (PMID 26252654, 2015). "Recent reports have implicated a role for CXCL1 in breast cancer." (PMID 25344051, 2014). "Similarly, increased tumoral expression of CXCL1 RNA is associated with metastatic disease, correlating with tumor grade and decreased survival of patients with ER-α positive breast cancer." (PMID 25344051, 2014). "CXCL1 is commonly overexpressed in cancer and stromal cells of various cancers, including breast cancer, colorectal cancer, prostate cancer, pancreatic ductal adenocarcinoma, and bladder cancer." (PMID 40527884, 2025). "In breast cancer, IL-17 has been shown to stimulate the production of several neutrophil-attracting chemokines, such as CXCL1, CXCL5, and CXCL8." (PMID 40486614, 2025). "In breast cancer, macrophage-derived CXCL1 activates an IGF1R/STAT3/HMGB1 axis that promotes autophagy-mediated paclitaxel resistance and inhibits apoptosis." (PMID 41465435, 2025). "On this basis, we found that senkyunolide H binds to CXCR2, inhibits the activation of CXCR2 by inflammatory factors (such as IL-8 and CXCL1), and blocks the pro-breast cancer effect of depression." (PMID 40839237, 2025). "Ionizing radiation increases CXCL1 expression in many cancers, such as breast cancer, glioblastoma multiforme, and non-small-cell lung cancer." (PMID 40427171, 2025). "First, we tracked CXCL8 and CXCL1 expressions across different breast cancer molecular subtypes using the HMS LINCS dataset." (PMID 40833805, 2025). "Ginsenoside panaxatriol reduces the activation of NF-κB in breast cancer cells and thus decreases the expression of chemokines, such as CXCL1 and CXC motif chemokine ligand 8 (CXCL8)/interleukin-8 (IL-8), increasing the effectiveness of paclitaxel." (PMID 40427171, 2025). "Recent studies have identified iCAF in several tumour types, including pancreatic cancer and breast cancer, using a variety of markers that encompass inflammatory cytokines and other genes (CXCL1, CXCL8, CXCL12, IL6, CFD, DPT)." (PMID 39757146, 2025). "Specifically, various growth factors and molecular pathways, such as TGF-β1/Smad, PI3 K/AKT, adipsin, CXCL1/8, CK 18+19, and interleukin-6, potentially contribute to the tumor microenvironment and tumorigenesis in breast cancer cells." (PMID 40399731, 2025). "In mammary carcinoma-associated fibroblasts, TGF-β negatively regulates CXCL1 expression through Smad2/3 and HGF/c-Met signaling mechanisms." (PMID 40490643, 2025). "Collectively, these finding provided in vivo evidence supporting that TAMs increase paclitaxel chemoresistance by inducing CXCL1-mediated autophagy in breast cancer." (PMID 39394189, 2024).
breast carcinoma (continued). "Previous studies demonstrated that CXCL1 induced autophagy-mediated chemoresistance in breast cancer cells by modulating HMGB1." (PMID 39394189, 2024). "CXCL1 can promote the migration and invasiveness of breast cancer by activating the transcription of SOX4 via the NF-κB pathway, resulting in the subsequent epithelial-mesenchymal transition (EMT) process." (PMID 38612764, 2024). "CXCL1 knockdown in TAMs demonstrated a remarkable chemosensitizing effect on breast cancer xenografts, along with blockage of IGF1R/STAT3/HMGB1 signaling in vivo." (PMID 39394189, 2024). "Altogether, BHS synergizes with paclitaxel to inhibit breast cancer growth and lung metastasis by suppressing EV‐Apo/CXCL1‐induced TAM infiltration and PD‐L1 expression in an immunocompetent mouse model." (PMID 39051750, 2024). "In this study, we found that EV‐Apo isolated from paclitaxel‐induced apoptotic breast cancer cells were enriched with CXCL1, which promoted the metastasis and chemoresistance of breast cancer by activating the TAM/PD‐L1 pathway." (PMID 39051750, 2024). "Taken together, these findings suggested that CXCL1 also promoted autophagy and chemosensitivity in paclitaxel-resistant breast cancer cells." (PMID 39394189, 2024). "Collectively, our research highlights the important role of TAMs/CXCL1 in mediating breast cancer chemoresistance through the regulation of autophagy, and proposes IGF1/IGF1R as a potential upstream signaling that governs autophagy via STAT3/HMGB1 activation." (PMID 39394189, 2024). "The top five genes (NAT1, PPM1H, AREG, ACSS1, CXCL1) with the greatest differences in Z-scores were evaluated in the PIK3CA mutant breast cancer samples from TCGA." (PMID 38802751, 2024). "Clinically, CXCL1 elevation was also closely correlated with poor chemosensitivity and recurrence‐free survival of breast cancer." (PMID 39051750, 2024). "This study aimed to explore the molecular mechanisms by which TAMs/CXCL1 induced autophagy-mediated chemoresistance in breast cancer." (PMID 39394189, 2024). "KC (CXCl1) promotes inflammation and metastasis by recruiting myeloid cells in breast cancer, including neutrophils." (PMID 38397942, 2024). "Herein, we demonstrated that paclitaxel chemotherapy elicited CXCL1‐enriched EV‐Apo from apoptotic breast cancer cells, which promoted the chemoresistance and metastasis of breast cancer by polarizing M2 macrophages through activating PD‐L1 signalling." (PMID 39051750, 2024). "Overall, these findings indicated that CXCL1 appeared to be a crucial factor in TAMs-CM to induce breast cancer chemoresistance and autophagy." (PMID 39394189, 2024). "In this study, we demonstrated that TAMs/CXCL1 promoted breast cancer chemoresistance by activating autophagy in vitro and in vivo." (PMID 39394189, 2024). "Most of the 11 TNF signaling pathway targets we tested were targets of breast cancer doxorubicin resistance, except for CXCL1." (PMID 39000182, 2024). "In contrast, the chronic inflammatory IL signature, including IL-4, IL-5, IL-10, IL-13, IL-17, and CXCL1, showed a significant prognostic effect across the whole cohort of breast cancer patients." (PMID 39456897, 2024). "Breast cancer tissues in TMA were utilized to investigate the clinical significance of CXCL1 and its relevance with HMGB1, IGF1R, and CD163 expressions." (PMID 39394189, 2024). "In the present study, it was demonstrated that TAMs/CXCL1 enhanced chemoresistance in parental or chemoresistant breast cancer cells through autophagic activation." (PMID 39394189, 2024). "IL-17A upregulated CXCL1 secretion in breast cancer cells, resulting in the enhanced migration, invasion, and increased expression of pAKT and pNF-κB." (PMID 38255960, 2024). "Both breast cancer cells treated with CXCL1 exhibited an increase in yellow and free red puncta with increasing doses, while the CXCL1 neutralizing antibody prevented the onset of autophagy induced by TAMs-CM." (PMID 39394189, 2024).